CCL2 (C-C motif chemokine ligand 2)
Diseases named in the same sentence as CCL2 in open-access papers (continued):
Sharing a sentence is not in itself a finding about the gene and the disease.
pancreatic cancer (continued). "The effect of HIF-1α on the inflammation and fibrosis of pancreatic cancer through regulating CCL2 has been shown in the present study." (PMID 27271610, 2016). "The potential contribution of CCL2 to pancreatic cancer progression is of major interest because CCL2 production correlated with the levels of macrophage content in transplanted tumors in vivo." (PMID 27191744, 2016). "It has been reported that the overproduction of CCL2 is closely related to macrophage infiltration in pancreatic cancer." (PMID 27191744, 2016). "The chemokine C- C chemokine receptor type 2 (CCL2) is responsible for the recruitment of C-C motif chemokine ligand 2 (CCR2)+ inflammatory monocytes from the bone marrow to the peripheral blood where they ultimately migrate to pancreatic cancer and become immunosuppressive TAMs." (PMID 40666494, 2025). "Similarly, a relatively high level of CCL2 expression was also observed in two human pancreatic cancer cell lines, PANC-1 and KP-4." (PMID 40700478, 2025). "In conclusion, this study elucidates the role of the IFN-γ/JAK/STAT1/CCL2/MMP13 pathway in exerting antitumor effects in pancreatic cancer by activating immune cells, which challenges the conventional understanding of CCL2 and MMP13 as promoters of tumor progression." (PMID 40909948, 2025). "The role of CCL-2 in the progression of pancreatic cancer has been of high interest for investigators given its potent induction of monocyte migration to the tumor site, and the production of CCL-2 correlates with macrophage presence in transplanted in vivo tumors." (PMID 39200298, 2024). "The enhanced immuno-oncolytic virus efficacy of TPV/∆66R/mIL-2 and TPV/∆66R/mCCL-2 may be attributable to CCL-2- and IL-2-mediated negative regulation of pancreatic tumor progression through stimulation of the innate immune response." (PMID 39200298, 2024). "Pancreatic tumor cells begin secreting CCL2 soon after malignant transformation." (PMID 38339310, 2024). "We found increased M1-like macrophage accumulation in estrogen-depleted mice, where elevated CXCL10 and CCL2 levels were observed, consistent with findings in a pancreatic cancer model where CXCL10/CXCR3 signaling was shown to maintain macrophages in the pro-inflammatory M1 phenotype." (PMID 39007345, 2024). "Investigators have also reported that CCL-2 may be an important negative regulator of pancreatic cancer progression." (PMID 39200298, 2024). "Furthermore, it has been reported that monocyte mobilization via the CCL2/CCR2 axis decreases survival in pancreatic cancer." (PMID 37371612, 2023). "In a mouse model of pancreatic cancer, HPSE overexpression was associated with increased macrophage expression of M2 cytokines IL-6, IL-10, CCL-2, VEGF, and macrophage scavenger receptor-2 (MSR-2), increased tumor size, and increased levels of tumor-infiltrating macrophages." (PMID 34461608, 2021). "The C-C motif chemokine ligand-2 (CCL2) also enables pancreatic cancer immune evasion." (PMID 33546207, 2021). "On the other hand, CCL2 production confirmed in neoplastic ducts of the pancreas could be a relevant negative regulator of pancreatic cancer progression." (PMID 32429318, 2020). "The monocytes recruited by CCL2 were found to mediate PNI of pancreatic cancer." (PMID 32064233, 2020). "Furthermore, serum CCL2 levels are positively correlated with tumor macrophage infiltration in pancreatic cancers." (PMID 32429318, 2020). "Moreover, small molecule inhibitors against CCL2 cognate receptor CCR2 are in clinical trials mainly in pancreatic cancers." (PMID 32455851, 2020). "The biological consequence of tumor macrophage infiltration induced by CCL2 in pancreatic cancer may be differed by adiposity." (PMID 29573228, 2018). "Pancreatic cancer is rich in stroma, which facilitate the secretion of CCL2." (PMID 27191744, 2016).
pancreatic cancer (continued). "Moreover, we show a previously unknown link between TGF-α, Ccl2, and NI in pancreatic cancer, using the herein reported, human-like neuroinvasive TPAC model and human data." (PMID 37607005, 2023). "Therefore, inhibition of CCL2 might be a new therapeutic approach for the prevention and treatment of pancreatic cancer." (PMID 26294325, 2015). "Targeting this signaling axis via CCR2 blockade or CCL2-neutralizing antibodies has been shown to slow tumor progression and shunt TAMs from the TME in several preclinical tumor models, including pancreatic cancer in vivo." (PMID 40282185, 2025). "Targeting ENSA-K63la or CCL2 enhances the efficacy of ICB therapy in murine and humanized pancreatic tumor models." (PMID 39883522, 2025). "Targeting mutant-KRAS, CCL2, or ENSA-K63la enhances the efficacy of ICB therapy in pancreatic tumor models." (PMID 39883522, 2025). "In our study, the candidates stood out as being exceptionally strongly regulated in the cocultures over the pancreatic cancer and RAW264.7 monocultures, namely the previously discussed CCL2 and CCL22 for Panc02 cells and CCL5 for PDA6606 cells." (PMID 40282185, 2025). "In pancreatic tumor cells, lactate induces K63 lactylation of endosulfine α (ENSA-K63la), a crucial step that triggers STAT3/CCL2 signaling." (PMID 39883522, 2025). "Utilizing a CCR2 blocker, PF-04136309, within an orthotopic mouse model of pancreatic cancer demonstrated the ability to decelerate tumor growth and metastasis by diminishing MDSC infiltration in tumor tissues via the CCL2/CCR2 pathway." (PMID 38756774, 2024). "Another study on pancreatic cancer showed that α-SMA+ CAF cells produce macrophage colony-stimulating factor 1 (M-CSF-1), IL-6, TGF-β, and CCL2 to promote monocyte recruitment and macrophage polarization into M2 macrophages." (PMID 39030445, 2024). "While CCL2 indirectly benefits pancreatic cancer, through fostering the creation of an immunosuppressive TME, CCL2 can also directly act on cancer cells in an autocrine fashion." (PMID 38339310, 2024). "We also quantified the mRNA content of the Ccl2 gene in granulocytes, monocytes, endothelial cells, mesenchymal cells, and cancer cells isolated from KPC and TPAC pancreatic tumors (n=3)." (PMID 37607005, 2023). "CCL2 contributes to insensitivity to ICB by recruiting monocytes and reducing CD8+ T-cell infiltration in pancreatic tumors." (PMID 36189283, 2022). "To confirm the increased population as TAMs, we sorted the CD11b + F4/80 + cells from the pancreatic tumors using a FACS sorter and quantified the expression of some TAM markers, such as HIF-1α, CCL2, and PECAM1, with qRT-PCR." (PMID 34150748, 2021). "CXCL1, CXCL5, CCL2, and IL-8 were significantly induced by TRAIL in lung, colorectal and pancreatic cancer cell lines." (PMID 31010082, 2019). "The CCL2/CCR2 axis plays an important role in monocyte recruitment in many cancer types, including pancreatic cancer." (PMID 27191744, 2016). "Recently, it was reported that CD40 activation on macrophages released interferon-γ and CCL2 and induced MMP-dependent fibrosis degradation in pancreatic carcinoma, resulting in the enhanced chemotherapy efficacy." (PMID 27655706, 2016). "To investigate whether CCL2 acts downstream of TMBIM1 and promotes pancreatic cancer cell proliferation and migration, we utilized the Capan-1 and PANC-1 cell lines." (PMID 40083936, 2025). "Interestingly, pancreatic cancer cells also appear to upregulate CXCL5 in response to gemcitabine chemotherapy, similar to how CCL2 is upregulated in response to radiotherapy." (PMID 38339310, 2024). "We next tested whether CCL2 directly induces phosphorylation of paxillin and treated SU.86.86 and T3M4 pancreatic cancer cells with 100 ng/mL of rCCL2 for 5, 15, and 25 minutes." (PMID 37607005, 2023).
pancreatic cancer (continued). "This is the case of the CCL2/CCR2 axis, which plays a role in the recruitment of monocytes in tumors: the CCR2 antagonist (PF-04136309) enhanced anti-tumor immunity, decreased tumor growth, and reduced metastasis in an orthotropic model of pancreatic cancer." (PMID 34209309, 2021). "The direct or indirect effects of IL-6, IL-8, IL-10, TGF-β, C-C motif chemokine ligand 2 (CCL2), C-X-C motif chemokine ligand 9 (CXCL9), and CXCL10, but not limited to those, on tumor immunity in patients with oral, breast, and pancreatic cancer have been investigated." (PMID 31281359, 2019). "CCL2 is known to promote angiogenesis in different cancers; hence, MAGEA3-mediated CCL2 overexpression in pancreatic cancer cells might have also indirectly contributed to the overall tumor growth in vivo, which warrants further investigation." (PMID 31287009, 2019). "Similar to CCL2, however, CCL5 expression is not exclusive to pancreatic cancer cells, especially as PDAC progresses." (PMID 38339310, 2024).
endometriosis (107 papers, 2007 to 2025). The growth of functional endometrial tissue in anatomic sites outside the uterine body. "In this way, increased levels of TNF-α, IL-6, IL-8, IL-10, VEGF, and MCP-1/CCL2, as well as different metalloproteinases (MMPs), are associated with the establishment and progression of endometriosis." (PMID 35164046, 2022). "Consistent with this is the association of CCL2 upregulation with immune tolerance in endometriosis, a mechanism suggested to act through its action on the FAS ligand, inducing apoptosis of T lymphocytes." (PMID 20707927, 2010). "Results from leave-one-out analyses are presented for the associations between MCP-1/CCL2 with PCOS and ILs-2 and -9 with endometriosis (respectively)." (PMID 39766252, 2024). "Method comparison plots are presented consisting of scatter plots and trendlines for the associations between MCP-1/CCL2 with PCOS and between ILs-2 and -9 with endometriosis (respectively)." (PMID 39766252, 2024). "In Bonferroni-corrected leave-one-out analyses, omitting single SNPs did not achieve statistical significance for exposures associated with PCOS (MCP-1/CCL2: p > 3.85 × 10−3, 0.05/13) or endometriosis (IL-2: p > 0.01, 0.05/5; IL-9: p > 8.33 × 10−3, 0.05/6)." (PMID 39766252, 2024). "Interleukin-8 (IL-8) and monocyte chemotactic protein 1 (MCP-1), encoded by CXCL8 and CCL2 respectively, showed higher expression levels in the eutopic endometrium of women with endometriosis." (PMID 35130311, 2022). "Our previous study demonstrated that macrophages are recruited to EMs lesions via CCL2 induced by ERβ and in turn promote the development of endometriosis." (PMID 35841069, 2022). "Among the chemokines, CCL2 (encoded MCP-1) is abundant in the PF and in the lesions of patients with endometriosis, and its cognate receptor (CCR2) is upregulated in monocytes." (PMID 35628223, 2022). "MCP‐1 and its receptor CCL2 have been shown to play a crucial role in the initiation and progression of endometriosis." (PMID 33325132, 2021). "Previous research has shown that ESR2 upregulates CCL2 via NF-κB signaling in endometriotic stromal cells and recruits macrophages to promote the pathogenesis of endometriosis." (PMID 34531861, 2021). "This is consistent with our observation that CCL2 concentrations are elevated in the PF from endometriosis patients as compared to healthy women as well as previous observations of many other investigators." (PMID 34360900, 2021). "PF from the women with endometriosis displayed significantly increased concentrations of CCL2, CXCL8 and CXCL9 as compared with the control subjects." (PMID 34360900, 2021). "This endometriosis animal model showed a human endometriosis phenotype, such as increased expression levels of Er-β, Ccl2, Ccl5, and Il-6." (PMID 33339236, 2020). "For example, inflammation mediators such as CCL2 have been found to be partially regulated by NFκB in endometriosis." (PMID 33121166, 2020). "Levels of CCL2 were previously found to be significantly correlated with the stage of endometriosis and were higher in women with endometriosis than in women with tubal infertility." (PMID 31636643, 2019). "MCP-1 (also called CCL2) regulates migration and infiltration of monocytes/macrophages, cells found in increased numbers in the peritoneal cavity in endometriosis." (PMID 30621017, 2019). "Nerves in the endometriosis lesion release chemicals like colony-stimulating factor-1 (CSF-1), chemokine ligand 2 (CCL-2), leukemia inhibitory factor (LIF), and pancreatitis-associated protein III (PAP-III), which induce the migration of macrophages toward the nerve ending." (PMID 40747182, 2025). "IL22 in the setting of endometriosis promotes proliferation of ESCs via secretion of CCL2 and IL-8." (PMID 38999962, 2024).
endometriosis (continued). "In addition, some scholars hold the view that the endometriosis-induced expression of monocyte chemotactic protein-1 (MCP-1, also known as chemokine ligand 2, CCL2) contributes to paracrine and autocrine activation and macrophage recruitment." (PMID 36865552, 2023). "CCL2 is a key chemokine responsible for chemotaxis/infiltration and activation of monocytes/macrophages, thus, our present results strongly argue for the role of the PF milieu in generation of pelvic inflammation in the course of endometriosis." (PMID 34360900, 2021). "The specific profile of inflammatory mediators dominant in endometriosis (high IL-1β, IL-6, IL-8, TNF-α, CCL2/MCP-1, MMPs) shows a striking resemblance to the canonical components of the SASP secreted by senescent cells." (PMID 41145947, 2025). "In endometriosis, signals from the DME (e.g., TGF-β1 and CCL2) drive TET3 overexpression, generating a unique Toe-Macs macrophage population that becomes dependent on elevated TET3 levels." (PMID 40794443, 2025). "SASP gene products identified by RNAseq include many inflammatory biomarkers that have been historically analyzed in endometriosis, including IL-1β, IL-6, IL-8, CCL5, TNF-α, CCL2, MMP3, HMGB1, p16, and p21." (PMID 38879630, 2024). "Lastly, while MCP-1/CCL2 and IL-9 are proposed as potential biomarkers for PCOS and endometriosis, respectively, supported by pre-clinical and observational data, their specificity in real-world clinical applications remains uncertain." (PMID 39766252, 2024). "Chemokines, like C-C motif chemokine ligand 2 (CCL2) and 5 (CCL5) which play a pivotal role in macrophage recruitment, are significantly increased in endometriosis lesions." (PMID 37447296, 2023). "MCP‐1 (CCL2) and its receptor CC motif chemokine receptor‐2 (CCR2) play a key role in endometriosis initiation and development." (PMID 36259314, 2022). "Among the top genes in the two key subnetworks, VEGFA, CXCL8, CCL2, IL1B and PTGS2 were also considered to be highly related to endometriosis in MalaCards." (PMID 35130311, 2022). "The levels of some investigated cytokines and chemokines, such as IL-6, IL-10, CCL2, CXCL8, and CXCL9, were significantly increased in PF from patients with endometriosis as compared to control." (PMID 34360900, 2021). "Concentrations of IL-6, IL-10, CCL2, CXCL8 and CXCL9 were significantly upregulated in the PF from women with endometriosis when compared to control women, whereas concentrations of other cytokines and chemokines were unaffected." (PMID 34360900, 2021). "Certain chemokines, especially CXCL8 (IL-8), CCL-2 (MCP-1), and CCL5 (RANTES), can serve as biomarkers identifying patients with endometriosis, but the accuracy of such tests can be improved by including other noninflammatory markers in the biomarker panel." (PMID 27294113, 2016). "Moreover, LUT can also regulate several signal transduction pathways, including NF-κB, AP1 and JAK–STAT, and it can inhibit macrophage recruitment to the endometriotic lesions by suppressing the secretion of CCL2 and CCL5 by endometriosis cells." (PMID 37447296, 2023). "Also, overexpression of MCP-1 (CCL2) and IL-1β in endometrium of women with endometriosis suggests increased infiltration of monocytes that differentiate to macrophages in this tissue in women with disease." (PMID 35421980, 2022). "Similarly, in the peritoneal fluid of women with endometriosis, levels of CXCL1, CXCL2, CCL2, MCP-3, and HGF were found to be significantly elevated compared to those in control individuals." (PMID 31636643, 2019). "Likewise, increased secretion of MCP1 (also known as CCL2) from PMs was reported in women with versus without endometriosis." (PMID 39141428, 2024).